CRP (C-reactive protein)
Diseases named in the same sentence as CRP in open-access papers (continued):
Sharing a sentence is not in itself a finding about the gene and the disease.
diabetes (continued). "The identified 42 blood clinical markers included some markers previously reported to be associated with microbiome diversity such as markers for diabetes (fasting insulin, P < 10−12), inflammation (hs-CRP, P < 10−14), liver function (ALAT, P < 10−9), and cholesterol (LDL, P < 10−16)." (PMID 33060586, 2020). "CRP is thought to be a risk factor for cardiovascular disease and diabetes among other things." (PMID 33029324, 2020). "In our study, higher CRP concentration was associated with higher odds of diabetes." (PMID 32665312, 2020). "CRP may be an important marker for assessment of risk of diabetes and risk for PAD and nephropathy in sub-Saharan Africans with and without diabetes." (PMID 32665312, 2020). "Based on the related risk of diabetes and coronary heart disease, CRP might be potentially recognized as a novel surrogate cardiovascular indicator and biomarker for antidiabetic agents." (PMID 31208420, 2019). "Indeed, CRP is a molecule involved in inflammatory and immune processes, which has been associated with aging-related diseases such as diabetes, cardiovascular diseases and hypertension." (PMID 31379754, 2019). "First, elevated plasma CRP has been associated with cancer prognosis, vascular atherosclerosis, insulin resistance, and type 2 diabetes mellitus that may impact overall survival." (PMID 31138314, 2019). "Furthermore, increased systemic inflammatory markers such as C-reactive protein (CRP) are related to the increased risk of type 2 diabetes mellitus (T2DM) and cardiovascular disease." (PMID 30665436, 2019). "CRP is an acute-phase protein, which rises in response to inflammation having a prognostic value in predicting the future risk of cardiovascular events and development of diabetes mellitus." (PMID 31176378, 2019). "In Model 3, adjusting for age, race/ethnicity, sex, body mass index, history of diabetes and cardiovascular disease, smoking status, and serum total cholesterol and CRP, people with aTRH had a 73% higher risk of cardiovascular mortality compared with the non-aTRH group [1.73 (1.34–2.23)]." (PMID 31023262, 2019). "However, previous studies have demonstrated beneficial effects of metformin on CRP in patients at high risk for diabetes after long-term intervention." (PMID 31821361, 2019). "CRP is elevated in various health conditions such as obesity and insulin resistance, and higher levels are also associated with an increased risk of developing CVDs and diabetes." (PMID 31052485, 2019). "Differences may also arise from the fact that the MetaboChip cohort excluded those with DM, perhaps minimizing the effect of variants that both predisposed to diabetes/obesity and increased CRP level." (PMID 31622379, 2019). "Pro-inflammatory molecules such as C-reactive protein (CRP), interleukin-6 (IL-6) and tumor-necrosis factor alpha (TNFα) are associated with major chronic conditions, including diabetes, cardiovascular diseases, and age-associated conditions such as frailty and dementia." (PMID 31426866, 2019). "This study was undertaken to assess the associations of C-reactive protein (CRP) with incident type-2 diabetes mellitus (T2DM) and to determine the joint effect of obesity and hypertension on them in the large-scale population-based Korean cohort of the Korean Genome and Epidemiology study (KoGES)." (PMID 30872696, 2019). "In addition, CRP, a history of diabetes mellitus, and positive inotropic usage were independent risk factors for AKI in the multivariate logistic regression analysis." (PMID 30971264, 2019). "Intermittent fasting is linked to improvement in the levels of biomarkers associated with cardiovascular health (blood pressure), diabetes (insulin and glucose levels), oxidative stress (8-isoprostane) and inflammation (IL-6, CRP)—suggestive of a systemic impact." (PMID 31426866, 2019).
diabetes (continued). "Moreover, C-reactive protein (CRP), a history of diabetes mellitus, and positive inotropric usage were independent risk factors for AKI in the multivariate logistic regression analysis." (PMID 30971264, 2019). "Additionally, dairy fat biomarkers were also inversely associated with diabetes-related outcomes, the inflammatory marker hs-CRP and the kidney marker uric acid." (PMID 31108924, 2019). "The correlation of CypA and CRP was before described and the role of both to predict the risk of coronary artery disease, or as markers of proinflammatory status in patients with diabetes was hypothesized." (PMID 31332225, 2019). "Our univariate analyses showed that five variables (age, diabetes, operation time, CRP and AFR) might be potential risk factors for SPCs." (PMID 31533682, 2019). "We conducted a cross-sectional study consisting of 945 siblings from 330 families collected by the Stanford Asian Pacific Program in Hypertension and Insulin Resistance (SAPPHIRe) to investigate associations between CRP polymorphisms, circulating CRP, diabetes, and glucose levels." (PMID 28801571, 2017). "Higher HbA1c levels were associated with higher CRP levels, pre-diabetes and T2DM." (PMID 29177105, 2017). "The best features, i.e. six biomarkers (adiponectin, C-reactive protein, ferritin, interleukin-2 receptor A, glucose, and insulin), were used in a PreDx diabetes risk score (DRS) model providing an AUC of 0.76 that increased to 0.78 when family history, age, BMI, and waist circumference were added." (PMID 28360826, 2017). "Since rs3093059 and rs1205 are associated with CRP level and CRP level is associated with diabetes prevalence and levels of fasting and 2-hour glucose, it is natural to investigate whether these two CRP-associated SNPs are associated with these traits." (PMID 28801571, 2017). "Furthermore, few studies investigating association of CRP polymorphisms with diabetes and glucose levels were conducted in population of Chinese ancestry." (PMID 28801571, 2017). "Since we successfully replicated the associations of CRP levels with CRP SNPs, diabetes, and glucose levels reported previously, the influence of lack of these confounding factors on our analysis might be not severe." (PMID 28801571, 2017). "Several studies have suggested that CRP-diabetes association could be largely explained by obesity, insulin resistance, deranged liver function and lower adiponectin levels." (PMID 28178951, 2017). "Since circulating CRP is significantly associated with diabetes and glucose levels, we aimed to investigate whether CRP polymorphisms are associated with these traits." (PMID 28801571, 2017). "Further efforts are needed not only to dissect the mechanism underlying the association between CRP gene and 2-hour glucose but also to investigate whether CRP gene plays a role in the pathogenesis of diabetes." (PMID 28801571, 2017). "CRP an inflammatory marker was significantly associated with diabetes duration (r = 0.29, P = 0.004), hyperglycemia (r = 0.65, P = 0.0001), poor glycemic control (r = 0.39, P = 0.0001), and diabetes complications." (PMID 28546831, 2017). "Then we investigated whether several SNPs of CRP gene are associated with diabetes and glucose levels." (PMID 28801571, 2017). "The inconsistent and modest associations between CRP polymorphisms and diabetes observed in previous and current studies might be due to genetic heterogeneity of diabetes." (PMID 28801571, 2017). "Moreover, the multivariate logistic regression analysis in this study revealed that hs-CRP, renal dysfunction, diabetes mellitus, STEMI, and cystatin C were independent risk factors of CIN as well." (PMID 27547760, 2016). "In CHD outcome model (efficacy endpoint), after adjusting for potential confounding covariates including age, gender, smoking status, SBP, LDL cholesterol, Lp(a), Hs-CRP, hypertension, diabetes and statins, aspirin therapy reduced the risk of CHD, with OR of 0.85 (95 % CI: 0.80-0.94, P < 0.05)." (PMID 27313113, 2016).
diabetes (continued). "In a large Danish COPD population study, an elevated WBC count in combination with elevated levels of CRP and fibrinogen was associated with a two- to four-fold increased risk of major comorbidities such as ischemic heart disease, diabetes, lung cancer, and pneumonia." (PMID 27258044, 2016). "However, after additional adjustment for fasting glucose, only CRP remained significantly associated with incident diabetes." (PMID 27581604, 2016). "Previous studies have reported that various inflammation markers, e.g., interleukin-6, tumor necrosis factor α (TNFα) and CRP are associated with diabetes It is believed that TNFα contributes to diabetes through its interaction with insulin signaling pathways and beta-cell function." (PMID 26891449, 2016). "Taken together, the Lanoh (both males and females) have higher risk for diabetes mellitus which may be associated with insulin resistance (in view of the high insulin and hs-CRP levels)." (PMID 27009064, 2016). "Risk factors, including age, sex, diabetes mellitus, smoking status, alcohol consumption, hs-CRP levels, and NIHSS scores, were significantly different between groups (P < 0.001, P < 0.028, P < 0.041, P < 0.008, P < 0.010, P < 0.003, and P < 0.001, respectively)." (PMID 27555819, 2016). "RIS was associated with older age, male, diabetes, H-type hypertension and CRP." (PMID 27164124, 2016). "Another confounding factor that could have influenced our results is the menarcheal age of the enrolled women, since earlier menarche was associated with elevated ALT, TG and CRP levels as well as increased risk of diabetes in a Brazilian study." (PMID 25986611, 2015). "Strong significance persisted among blacks even after multivariable adjustment, indicating that SDB has a residual effect in blacks independent of lifestyle risk factors as well as other hypertension risk factors such as total cholesterol C-reactive protein levels, and diabetes." (PMID 26064690, 2015). "Similarly, RDW was positively associated with CRP level in a study based on a nationwide database of people with diabetes." (PMID 25961836, 2015). "In the third model after adjustment for age, CRP, a history of cardiovascular disease and diabetes mellitus, both receptors remained independently associated to outcome, the hazards ratio for sTNFR1 (HR: 1.51, 95% CI: 1.30–1.77) again being higher than for sTNFR2 (HR: 1.13, 95% CI: 1.06–1.20)." (PMID 25823004, 2015). "Childhood BMI was associated with risk of adult obesity, metabolic syndrome, hyperglycaemia or diabetes, and elevated high-sensitivity CRP, while risk of hypertension, raised triglycerides and reduced HDL cholesterol was predominantly affected by BMI gain from childhood to adulthood." (PMID 25880559, 2015). "We excluded participants who were diagnosed with diabetes by a physician or were taking diabetes medication at baseline because treatment for diabetes might affect the association between CRP and HbA1c." (PMID 25994228, 2015). "Few studies have estimated to what extent CRP could improve the discrimination power of models containing conventional risk factors for diabetes." (PMID 24819157, 2014). "After adjusting for diabetes, education, medication, alcohol consumption, blood pressure, stroke, smoking and MI, the strength of the association between log(CRP) and cognitive decline remained similar to the crude age- and sex-adjusted model (OR: 0.57, 95% CI: 0.30–1.04, P = 0.08)." (PMID 24305621, 2014). "Previous cross-sectional studies have linked CRP with prediabetes and diabetes in Chinese." (PMID 24819157, 2014). "There is also evidence indicating that increased levels of CRP may not only reflect the presence of inflammation, but also may promote inflammation and the risk for features of the metabolic syndrome and diabetes." (PMID 25010431, 2014). "CRP measurements may also identify Type 2 diabetes patients for whom treatment of cardiovascular risk factors or diabetes may be particularly beneficial." (PMID 25163828, 2014).
diabetes (continued). "This observed pro-inflammatory state might be related to insulin resistance, because it has been demonstrated that the plasma us-CRP might be a marker of risk for the development of macrovascular disease and diabetes mellitus, even independently of obesity." (PMID 24443817, 2014). "According to multivariate logic analyses, after adjustment for cardiovascular risk factors such as age, gender, SBP, BMI, smoking, diabetes duration, HbA1c, CRP, IL-6, LDL and medication, HIF-1α levels still significantly and independently predicted the presence of CAC." (PMID 24564828, 2014). "However, the associations of sleep disturbances with heart failure, diabetes, elevated CRP and fibrinogen disappeared." (PMID 25093413, 2014). "CRP has been shown to be strongly associated with diabetes in recent years." (PMID 24667814, 2014). "Inflammation, which is the body's normal response to injury and disease, affects insulin signaling and increases beta-cell death, and markers of inflammation such as raised blood levels of C-reactive protein and interleukin 6 are associated with future diabetes risk." (PMID 23843750, 2013). "At baseline there were independent associations between GDF-15 and current smoking, diabetes mellitus, biomarkers of cardiac (high-sensitivity troponin-T, NT-proBNP) and renal dysfunction (cystatin-C) and inflammatory activity (C-reactive protein), and previous cardiovascular disease (CVD)." (PMID 24312445, 2013). "However, vascular disease was associated with increased age (r = 0.21; p = 0.049) and diabetes and CRP were negatively correlated with presence of LVH (r = 0.22; p = 0.046)." (PMID 23717629, 2013). "In the logistic regression modelling, SBP, serum uric acid, CRP and diabetes were significantly associated with albuminuria and it was marginally significant for GGT (p = 0.054) while there was significantly inverse relationship between serum albumin and albuminuria." (PMID 23947772, 2013). "Diabetes, hypertension, high cholesterol and hs-CRP are all risk factors of ischemic stroke." (PMID 23737893, 2013). "We have to keep in mind that high CRP values could increase the risk for the development and progression of diabetes, and if they would be reduced, a better control of diabetes and periodontal disease could be achieved." (PMID 22322513, 2012). "In the Nurses’ Health Study, serum ferritin levels and the sTfR-to-ferritin ratio were associated with an approximately 2.5-fold higher diabetes risk in the highest vs lowest quintile after controlling for C-reactive protein and various conventional risk factors of diabetes." (PMID 22752055, 2012). "As discussed, the inflammatory biomarker hs-CRP associates with diabetes mellitus." (PMID 22194960, 2011). "Higher mean age, female gender, non-white race/ethnicity, country of origin outside the U.S., lower mean education level, low BMI (<25 kg/m2) and high BMI (≥30 kg/m2) compared to medium BMI (25≤ BMI <30), reported diabetes and high CRP level (≥0.3 mg/dL) were associated with CMV seropositivity." (PMID 21379581, 2011). "However, our findings appear qualitatively very different from the rather disappointing results recently obtained by Mendelian randomization approaches pertaining to the role of C-reactive protein in the causation of coronary heart disease or diabetes." (PMID 21799821, 2011). "Patients admitted to our CPU have risk factors for coronary artery disease, such as diabetes, and therefore this population may have increased CRP values when compared to a patient population that lacks these risk factors for cardiac disease." (PMID 21702934, 2011). "We were able to study how GI and GL were associated with CRP and type 2 diabetes in a prospective cohort study with a high response rate, with a long follow-up period, with confirmed diabetes cases, and with available information on CRP concentration at baseline of a large population." (PMID 21804937, 2011).
diabetes (continued). "In this population-based cross-sectional Chinese study, we found that the elevated GGT concentrations were independently associated with the presence of diabetes defined by the glucose criterion in both men and women, while the effect of elevated CRP was significant only in obese women." (PMID 21076541, 2010). "Elucidation of the relationship between IR and CRP concentration may lead to an improved recognition of individuals at risk for future diabetes and CVD risk and may help in identification of novel therapeutic targets." (PMID 20482756, 2010). "Using a combination of central monitoring and personal microenvironment monitoring data for PM2.5, a significant association was reported between CRP and ambient levels, particularly among persons with diabetes, obesity, and hypertension, including combinations of these conditions." (PMID 20123638, 2010). "An association between CRP levels and diabetes has been reported in other studies." (PMID 20847810, 2010). "Several possible reasons might explain our finding that CRP was associated with diabetes only in obese women, and the main factors are presumably sex differences regarding body composition and sex hormone levels." (PMID 21076541, 2010). "Further adjustment for risk factors (alcohol use, BMI, CRP, diabetes mellitus, fasting time, LDL-cholesterol, MPO, smoking, systolic blood pressure, plasma vitamin-C, vitamin supplement use, waist circumference and triglycerides (non-fasting) did not substantially alter the observed relationship." (PMID 19710913, 2009). "It is important to note that rs10757278 and linked SNPs in high LD (e.g. rs1333049) are associated with family history of atherosclerotic disease, but not other traditional risk factors including body mass index, diabetes, tobacco use, blood pressure, C-reactive protein or lipid levels." (PMID 19343170, 2009). "As evidence accumulates, the guidelines may increasingly incorporate biomarkers; the American Heart Association has already noted in a scientific statement that risk assessment in diabetes may include biomarkers such as coronary calcium or CRP in selected patients." (PMID 41567175, 2026). "Moreover, confounding effects of comorbidities (diabetes mellitus) and therapeutic interventions (antibiotic administration) may obscure causal associations between CRP levels and invasive syndrome outcomes." (PMID 41048965, 2025). "Elevated GlycA concentrations have been shown to predict the risk of type 2 diabetes mellitus, cardiovascular disease, and all-cause mortality, and both GlycA and GlycB have been suggested to better reflect inflammation than traditional inflammatory markers such as C-reactive protein (CRP) and IL-6." (PMID 39515756, 2025). "Moreover, there is robust evidence that CRP is linked to several chronic diseases which are leading causes of mortality worldwide, like cardiovascular disease, chronic kidney disease, cancer, and diabetes mellitus." (PMID 40362763, 2025). "When LDL cholesterol, HOMA for insulin resistance, and C-reactive protein were added as single mediators in the mediation analysis (simple mediation), all of the three tested mediators were found to play a role in mediating the association between triglycerides and diabetes." (PMID 38611646, 2024). "CRP, an acute phase protein, is a sensitive marker of systemic inflammation linked to various afflictions including diabetes mellitus (DM), cardiovascular disease, and overall cancer risk (including breast cancer, melanoma, and cervical and colon cancer)." (PMID 38807790, 2024). "Interestingly, while our study did not reveal a significant association between plantar fasciitis and other cardiovascular risk factors such as hypertension, dyslipidemia, or diabetes, we did find a significant association between elevated CRP levels and these conditions." (PMID 38983990, 2024).